RNU1-98P (RNA, U1 small nuclear 98, pseudogene)
Gene: Small nuclear RNA gene on chromosome 21 (16,718,998 to 16,719,157, forward strand). Ensembl gene ENSG00000239023.
Homologues: Orthologues: chimpanzee U1 (96% identical), macaque U1 (92% identical), guinea pig U1 (77% identical), rat LOC120102023 (68% identical), mouse Gm25308 (66% identical). Paralogues in human: RNU1-1 (83% identical), RNU1-2 (83% identical), RNU1-27P (83% identical), RNU1-28P (83% identical), RNU1-3 (83% identical), RNU1-4 (83% identical), RNVU1-18 (83% identical), RNVU1-29 (83% identical), RNVU1-31 (83% identical), U1 (83% identical), RNVU1-28 (82% identical), RNVU1-7 (82% identical), and 134 more.